SIRT1 (sirtuin 1)
Diseases named in the same sentence as SIRT1 in open-access papers (continued):
Sharing a sentence is not in itself a finding about the gene and the disease.
metabolic disorders (continued). "Moreover, artificial SIRT1 activators, such as SRT2104, are currently under clinical investigation, with future potential therapeutic applications in the field of cardiovascular and metabolic diseases." (PMID 38304233, 2023). "Accordingly, SIRT1 activation by the polyphenol resveratrol and several small molecules have been shown to provide protection against NAFLD and T2DM in rodent models, and may be beneficial in human metabolic disease." (PMID 35203484, 2022). "Sirt1 is an NAD+-dependent type III histone deacetylase, which can catalyze the deacetylation of histone and non-histone lysine residues, and plays a vital role in regulating cell apoptosis, the occurrence and development of tumors, metabolic diseases and anti-aging." (PMID 35582617, 2022). "Given its pivotal role in the control of energy expenditure, it is not surprising that a dysfunctional AMPK/PGC-1α/Sirt1 signaling axis should be responsible for reduced muscle energy expenditure, as occurs in aging and in metabolic disorders, such as type 2 diabetes (T2D)." (PMID 36139463, 2022). "However, animal models do not mimic the pathogenesis of human metabolic diseases and further studies on human tissues will be required to determine what controls SIRT1." (PMID 26890260, 2016). "Our results show that, even after the exclusion of underweight patients from the sample, SIRT1 maintained a positive role in regulating TBS, the bone structure most exposed to the effects of metabolic disorder, and sclerostin has a negative impact on BMD." (PMID 35267956, 2022). "SIRT1, a nonamide adenine dinucleotide (NAD+)-dependent protein deacetylase, acts as an important modulator of metabolic pathways and plays a critical role in the pathophysiology of many metabolic diseases." (PMID 33343352, 2020).
neurodegenerative disease (204 papers, 2008 to 2026). A disorder of the central nervous system characterized by gradual and progressive loss of neural tissue and neurologic function. "Disruptions in the precise regulation of the Sirt-1/Nrf2 signaling cascade have been linked to the progression of neurodegenerative diseases, including PD." (PMID 41494036, 2026). "SIRT1 has been proven beneficial in neurodegenerative diseases by regulating their pathogenic mediators, involving OS, inflammation, mitochondrial dysfunction, cellular apoptosis, and senescence." (PMID 38987448, 2024). "Studies have shown that SIRT1 can reduce the damage caused by neurodegenerative diseases by regulating the apoptosis of neurons." (PMID 37718350, 2024). "SIRT1 is encoded by the SIRT1 gene, whose polymorphisms are related to physiological aging and neurodegenerative diseases." (PMID 37039942, 2023). "Conversely, the inactivation of Sirt1 has shown potential to ameliorate the mitochondrial apoptosis pathway, which is implicated in the pathogenesis of aging, metabolic disorders, and neurodegenerative diseases." (PMID 37622049, 2023). "There is also evidence that toxic proteins associated with neurodegenerative diseases can also reduce the expression of SIRT1, or directly interact with SIRT1 protein to inhibit its affinity with substrates and increase the acetylation of their substrates." (PMID 34616289, 2021). "SIRT1 levels are associated with neurodegenerative diseases which have a progressive and severe reduction in neuronal cells." (PMID 34377051, 2021). "Studies have shown that SIRT1 can reduce the damage caused by neurodegenerative diseases by regulating the apoptosis of neural cells." (PMID 33269110, 2020). "Sirtuin type 1 (SIRT1) is an enzyme that deacetylates proteins including transcriptional factors and associates with neurodegenerative diseases, such as AD." (PMID 32310828, 2020). "Sirtuin 1 (SIRT1) plays an important role in synaptic plasticity and cognitive performance, and its abnormal reduction is associated with cognitive dysfunction in neurodegenerative diseases." (PMID 32148659, 2020). "The effects of 6-OHDA-induced neurotoxicity is linked to modulation of the antiaging gene Sirtuin 1 (Sirt 1), which is important to neurodegenerative diseases such as PD." (PMID 32670009, 2020). "Alterations of the level of Sirt1 expression were associated with the outcomes of several metabolic and neurodegenerative diseases, cancer and aging." (PMID 33203121, 2020). "Previous studies showed that SIRT1 and autophagy were closely associated with degenerative diseases." (PMID 33363176, 2020). "A decrease in SIRT1 levels and activities is related to inflammation-associated diseases, including various neurodegenerative diseases." (PMID 32802267, 2020). "Sirtuin refers to a protein family that is homologous with the silent information regulation 2 (Sir2), and Sirtuin 1 (SIRT1) is the closest mammalian homologue of the yeast Sir2 that linked to neurodegenerative diseases." (PMID 29561961, 2018). "SIRT1, a protein deacetylase, is the member of the sirtuin protein family that was implicated in several human metabolic and degenerative diseases." (PMID 27322180, 2016). "Modulation of neurodegenerative diseases by Sirt1 is associated with improvement of oxidative stress and neuronal inflammation." (PMID 21639917, 2011). "The underlying importance of SIRT1 in protecting against neurodegenerative disease may be related to its regulation." (PMID 37456463, 2023). "In addition to PD, SIRT1 has been implicated in the pathophysiology of other neurodegenerative diseases." (PMID 33269110, 2020). "Sirt-1 and Sirt-2 are stress induced proteins that have been implicated in defense mechanisms against agents that may induce oxidative injury, and its induction represents a common feature in a number of neurodegenerative diseases." (PMID 24498895, 2013).
neurodegenerative disease (continued). "In particular, class I, II, and III HDACs such as HDAC3, HDAC4/5, and Sirtuin 1(Sirt1), respectively, have been shown to have critical roles in transcription repression during aging and neurodegenerative diseases." (PMID 40662679, 2025). "This activation of SIRT1 and reduction in γ-secretase suggested a holistic approach for addressing neurodegenerative diseases with Syzygium aromaticum." (PMID 40149988, 2025). "Another possible mechanism by which RSV mediates neuroprotective effects is through the activation of the sirtuin 1 pathway (SIRT1), which plays an essential role in regulating cell function by deacetylating important substrates in neurodegenerative diseases." (PMID 41080744, 2025). "Many flavonoids have been suggested to possess SIRT1-promoting capabilities, helpful to counteract inflammation in several degenerative diseases, as well as flavonoid-C-glycosides." (PMID 40076701, 2025). "Studies have shown that activation of SIRT1 can ameliorate symptoms of neurodegenerative diseases such as AD and PD, and enhance the brain’s resilience to cerebral ischemia-reperfusion injury." (PMID 40003583, 2025). "SIRT1 has been shown to modulate microglial activation and reduce neuroinflammation, which is essential for mitigating the progression of neurodegenerative diseases." (PMID 41517346, 2025). "Accordingly, activation of SIRT1 is actively pursued as a promising therapeutic strategy for managing neurodegenerative diseases." (PMID 39644364, 2024). "As oxidative stress and inflammation are known to have a role in the incidence of neurodegenerative diseases, the SIRT1/Nrf2/HO-1 pathway possesses an attractive target for the treatment of ADHD diseases." (PMID 39273230, 2024). "NeuroHeal, an AI-designed compound to target neurodegenerative diseases, has been shown to activate both the SIRT1 and the PI3K/Akt signaling pathways, which converge on FOXO3 deacetylation and phosphorylation." (PMID 37253984, 2024). "SIRT1 is a deacetylase, and the benefit of SIRT1 in neurodegenerative diseases was first reported by Graff." (PMID 36808393, 2023). "SIRT1 was already mentioned here as an epigenetic regulator performing important functions in neurodegenerative diseases, including AD, with an rSNP (rs1053224730) found in its promoter." (PMID 37175659, 2023). "Resveratrol and SIRT1 were reported to participate in pathophysiology of degenerative diseases in CNS and retina." (PMID 37670386, 2023). "By these pathways, SIRT1 can reduce the generation andaggregation of misfolded proteins that are essential to the etiologyof neurodegenerative diseases, including amyloid beta and tau." (PMID 37744807, 2023). "The pivotal role of SIRT1 was widely established in cellular senescence and neurodegenerative diseases, including AD." (PMID 37175659, 2023). "In the context of neurodegenerative diseases, a plethora of evidence confirmed SIRT1-mediated neuroprotective effects of resveratrol." (PMID 36237161, 2023). "As a survival factor against the aging process, Sirt1 has been shown to exert neuroprotective effects in the neurodegenerative diseases, such as AD, PD, and Huntington’s disease." (PMID 37622049, 2023). "The SIRT1/AMPK axis is increasingly being recognized by researchers as a potential therapeutic target in neurodegenerative diseases where autophagy and mitophagy are impaired." (PMID 37456463, 2023). "Ginsenosides from Panax japonicus inhibit oxidative stress and apoptosis and improve cognitive function by regulating Nrf2 and SIRT1 pathways related to neurodegenerative diseases in D-galactose-induced neuronal injury." (PMID 37686071, 2023). "SIRT1 plays a role in neurodegenerative diseases and is considered a suppressor of oxidative stress in PD." (PMID 37446264, 2023).
neurodegenerative disease (continued). "Recently, sirtuin-1 (SIRT1) has emerged as a potential therapeuticprotein target for neurodegenerative diseases, owing to its capacityto enhance neurogenesis and promote cellular longevity." (PMID 37744807, 2023). "Mitochondrial dysfunction is involved in aging and various degenerative diseases, and SIRT1 can regulate mitochondrial biosynthesis and metabolism, repair mitochondrial loss and maintain mitochondrial stability." (PMID 37742223, 2023). "Further studies concluded that baicalein prevented neurotoxicity associated with PD by stimulating mitophagy via the SIRT1/AMPK axis, highlighting it as a therapeutic target in neurodegenerative diseases associated with impaired autophagy." (PMID 37456463, 2023). "Increasing studies indicate that the expression of SIRT1 is significantly diminished in aging, metabolic, and neurodegenerative diseases, leading to oxidative stress." (PMID 36035216, 2022). "Upregulation of the SIRT1 or activation of the SIRT-1 activity has been noted for the enhanced cellular protection against many age-related diseases, including neurodegenerative diseases, i.e., PD." (PMID 35935335, 2022). "SIRT1 activity is recognized to have neuroprotective properties in neurodegenerative diseases and psychiatric disorders, but little is known about its role in the development of POCD." (PMID 36437988, 2022). "Changes in SIRT expression in neurodegenerative disorders and modulation of SIRT1 levels and/or activity is observed in models of aging and neurodegenerative diseases." (PMID 36432638, 2022). "As the most conserved mammalian NAD+-dependent protein deacetylase, SIRT1 has a number of important functions in the brain, including regulation of late stage of neural development and protection against a number of neurodegenerative diseases." (PMID 34042046, 2021). "Although sirtuins have been involved in immune activity and metabolic regulations, SIRT1, a NAD-dependent protein deacetylase, has been implicated in the pathogenesis of various neurodegenerative diseases including MS." (PMID 35002930, 2021). "Because many studies in animal models of demyelinating and neurodegenerative diseases have shown that SIRT1 induction can ameliorate the course of the disease." (PMID 34202956, 2021). "SIRT1 activation by the use of transgenic mice or viral vectors demonstrated protection in different neurodegenerative diseases such as ALS, AD, and HD and also after nerve injury." (PMID 33578870, 2021). "For example, SIRT1 activators have been proposed for treating a range of diseases and disorders such as aging, oxidative stress, diabetes, obesity, neurodegenerative diseases, cardiovascular disease and inflammation." (PMID 33669990, 2021). "SIRT1 participates in many age-related processes and disorders, such as neurodegenerative diseases and cardiovascular diseases, etc.." (PMID 33809718, 2021). "AMPK and SIRT1 can attenuate age-related telomere shortening through PGC-1α suggesting beneficial role of AMPK/SIRT1 activation on neurodegenerative diseases." (PMID 34206738, 2021). "The neuroprotective effect of SIRT1 has been confirmed in craniocerebral trauma, ischaemic injury, and many neurodegenerative diseases." (PMID 34721636, 2021). "SIRT1 have a positive influence on DNA repair thereby genomic instability, suggesting alleviating effect of SIRT1 activation on neurodegenerative diseases." (PMID 34206738, 2021). "The SIRT1/Nrf2 signaling pathway is an important signaling pathway to balance oxidative stress, which is actively involved in various neurodegenerative diseases." (PMID 34440032, 2021). "As discussed in the previous section, SIRT1 plays an important role in the progression of neurodegenerative diseases, such as AD and PD." (PMID 33014276, 2020). "Previous studies proved that quercetin had protective effect on many degenerative diseases via activating autophagy and promoting the expression of SIRT1." (PMID 33363176, 2020).
neurodegenerative disease (continued). "Studies have reported that increased SIRT-1 expression is related to reduced LPS-induced synaptic dysfunctions, suggesting a potential intervention for oxidative stress-related neurodegenerative diseases." (PMID 32831997, 2020). "Compelling evidence has indicated that SIRT1 plays an important role in neurodegenerative diseases and cognitive dysfunction." (PMID 33029280, 2020). "A reduction in Sirt1 expression has been related to cardiovascular and neurodegenerative diseases such as Alzheimer’s and Parkinson’s, and with some metabolic diseases such as obesity and diabetes." (PMID 33203121, 2020). "In recent years, studies into neurodegenerative diseases have found that SIRT1 can reduce the degeneration of human nucleus pulposus cells by inducing autophagy." (PMID 33269110, 2020). "A previous study found that SIRT1 activity was downregulated in the brains of patients with neurodegenerative diseases including PD." (PMID 32848564, 2020). "Quercetin, a natural flavonoid possessing a specific effect of autophagy stimulation and SIRT1 activation, showed some protective effect on a series of degenerative diseases." (PMID 33363176, 2020). "The pharmacological SIRT1 activator or inhibitor participant in the regulation of neuroinflammation and neurodegenerative diseases has been reported." (PMID 33014276, 2020). "The activity of SIRT1 was observed to be downregulated in patients with PD and other neurodegenerative disease patients." (PMID 31214610, 2019). "In conclusion, we provide a novel perspective for the prediction of the therapeutic benefits of the modulation of SIRT1- and nucleolar-dependent pathways in metabolic and neurodegenerative diseases." (PMID 31110473, 2019). "Beneficial effects of SIRT1 activation using genetic manipulation and pharmacological treatment have been reported in various animal models for neurodegenerative diseases." (PMID 30416425, 2018). "Like other neurodegenerative diseases, the role of SIRT1 has been investigated in the context of HD pathology." (PMID 30532738, 2018). "In this review, we focus on the role of SIRT1 in the neuroendocrine system and neurodegenerative diseases." (PMID 30416425, 2018). "Accumulating evidence indicate that high levels of SIRT1 exhibit neuroprotective roles in several neurodegenerative diseases." (PMID 29508282, 2018). "As an inflammatory regulator in PD and potentially other neurodegenerative diseases, SIRT1's deacetylase activity protects against pro-apoptotic inflammatory signaling." (PMID 30532738, 2018). "The evidence of the beneficial effects of SIRT1 obtained from animal models and human studies imply that SIRT1 activation can be a potential therapeutic treatment for neurodegenerative diseases." (PMID 30416425, 2018). "In some neurodegenerative diseases, a number of neuropeptide systems in the hypothalamus are affected from activity of SIRT1 which indicate an impact on metabolism." (PMID 30374331, 2018). "There are seven mammalian Sirtuins (SIRT1-7) that play important roles in stress response, aging, and neurodegenerative diseases." (PMID 29249955, 2017). "Some recent studies have found that the pharmacological activation or upregulation of Sirt1 expression showed neuroprotective effects in several models of neurodegenerative diseases." (PMID 28356158, 2017). "Previous studies have shown that activation of SIRT1 plays an important neuroprotective role in neurodegenerative diseases." (PMID 29375306, 2017). "Sirtuin1 (SIRT1) regulates epigenetic, DNA repair, aging, and programmed cell death and defends against neurodegenerative diseases." (PMID 25247581, 2014). "SIRT1 also deacetylates tau and prevents tauopathy that is evident in several neurodegenerative diseases." (PMID 25247581, 2014).